INS (insulin)
Diseases named in the same sentence as INS in open-access papers (continued):
Sharing a sentence is not in itself a finding about the gene and the disease.
Insulin resistance (continued). "After controlling for age and BMI, Ang-2 levels were associated with levels of sTie-2, diastolic blood pressure, plasma insulin, homeostasis model assessment of insulin resistance (HOMA-IR), creatinine, glomerular filtration rate (GFR), and gamma-glutamyl transferase (GGT) (all p < 0.02)." (PMID 21699724, 2011). "Beta-cell hypertrophy may also contribute to the increase in beta-cell mass as a means of adaptation to an increased insulin demand due to insulin resistance in diabetic subjects." (PMID 21818396, 2011). "In addition, knockout of each PKCθ or PKCε genes in mice enhances insulin signalling and glucose tolerance, and protect against fat induced insulin resistance." (PMID 22046423, 2011). "Furthermore, lifestyle intervention in conjunction with rosiglitazone or placebo therapy results in a significant decrease in insulin and insulin resistance (HOMA-IR)." (PMID 22035351, 2011). "In addition, plasma insulin concentrations in DU6 fed n-6 HFD were increased suggesting development of insulin resistance." (PMID 21835020, 2011). "Since insulin resistance is a major physiological consequence of obesity and also promoted by some inflammatory factors and adipokines, the insulin-stimulated incorporation of [14C]glucose into glycogen was determined in the attached HPCs cultured alone or co-cultured with iATEs and eATEs." (PMID 21687689, 2011). "First, the results from systemic insulin resistance may be influenced by several factors, besides the muscle, such as free fatty acids, cytokines and other insulin targets like adipose tissue and liver." (PMID 21526994, 2011). "Interestingly, administration of L-NMMA significantly and partially reversed the effects of CYP2J3 gene delivery on serum insulin, insulin resistance (HOMA-IR) and urine osmolarity in fructose-treated rats (all P < 0.05)." (PMID 22189162, 2011). "Moreover there were relation between insulin resistance, adiposity and Alzheimer due to insulin advanced product of glycosylation, cerebral vascular disease and product of adipose tissue." (PMID 21569551, 2011). "This study demonstrates that defects in insulin secretion rather than defects in insulin resistance explain the marketed difference in susceptibility to T2DM in the B6.apoE-/- and BALB.apoE-/- mouse model." (PMID 22204493, 2011). "Thus, it is imperative to provide new targets achieving equal and/or superior effects on insulin to control glycemia with less insulin resistance." (PMID 19095661, 2011). "However, CTSD will enhance receptor-mediated insulin degradation in vivo, thus inducing insulin resistance." (PMID 21689475, 2011). "These conclusions are strongly supported by the results obtained in the TG mice which showed overall increased insulin sensitivity, and in particular a delayed development of insulin resistance on the high-fat diet resulting in increased longevity on these diets." (PMID 21070590, 2011). "Plasma insulin levels and insulin resistance correlate inversely with ghrelin." (PMID 21676224, 2011). "Since several reports have shown that endothelial dysfunction is associated with insulin resistance, the aim of the present study was to investigate the role of sildenafil in NO production and changes in insulin signaling in HUVECs in basal and insulin resistance conditions." (PMID 21297971, 2011). "Besides an increased β-cell mass during the adaptation to insulin resistance, the most immediate response is the optimisation of the insulin secretion." (PMID 22208362, 2011). "In this instance, visfatin may, potentially, be a marker of insulin resistance, where the cell perceives lower levels of insulin and greater visfatin production arises, as a result." (PMID 21694775, 2011). "The second alternative hypothesis is the fetal insulin hypothesis which proposes that genetically determined insulin resistance results in impaired insulin-mediated growth in the fetus, as well as insulin resistance in adult life." (PMID 21771322, 2011).
Insulin resistance (continued). "Although insulin resistance is a major focus in type 2 diabetes associated with adipose and muscle tissue, our understanding of the effects of reduced insulin support to sensory neurons is surprisingly lacking." (PMID 21754917, 2011). "Long-term treatment with insulin may induce insulin resistance, a physiological state that is representative of chronic management of metabolic imbalance." (PMID 21966386, 2011). "Thus, in all these states insulin resistance leads to an increased production of insulin to maintain euglycemia." (PMID 22208362, 2011). "Studies in male mice have shown that BPA may also stimulate insulin biosynthesis and secretion through ERα, leading to hyperinsulinemia and insulin resistance." (PMID 22046388, 2011). "Regardless of HIV status, men with metabolic complications that included peripheral insulin resistance required a higher fasting plasma insulin concentration to achieve the same basal rate of myocardial glucose utilization as men without metabolic complications." (PMID 22151886, 2011). "The activity and antigen of PAI-1 associated with increased insulin levels (b = 1.941, P = 1.2 × 10-4; b = 1.614, P = 0.015), insulin resistance (b = 1.393, P = 2.2 × 10-4; b = 1.318, P = 0.007), and decreased insulin sensitivity (b = -1.963, P = 1.1 × 10-4; b = -1.637, P = 0.012)." (PMID 21414238, 2011). "However, insulin resistance parameters—including fasting insulin and HOMA-R—and numbers of WBCs were significantly increased among patients with sarcopenic visceral obesity compared with normal men and women." (PMID 21931785, 2011). "Human and mouse TCR has been shown to mimic insulin and its receptor and could contribute to insulin resistance." (PMID 21901158, 2011). "In the presence of insulin resistance, glucosehomeostasis is preserved by compensatory hyperinsulinemia, with type 2 diabetes ensuingonly when beta-cells fail to secrete sufficient insulin to adequately counteractimpaired insulin sensitivity." (PMID 21573217, 2011). "Furthermore, the histone deacetylase (HDAC) SIRT1, by virtue of its role in inflammatory responses, adipokine secretion and its interaction with the insulin signaling pathway, is suggested to have therapeutic benefit in treating insulin resistance." (PMID 21655096, 2011). "Thus, subjects with IFG appeared to have higher levels of insulin and insulin resistance compared with those with NFG, but retained pancreatic beta-cell function." (PMID 22363877, 2011). "High insulin concentrations in fasting and fed states trigger insulin resistance." (PMID 21860615, 2011). "Many reports suggested that PPAR alpha activation could improve the peripheral insulin resistance by relieving lipid-mediated inhibition of insulin-stimulated glucose disposal in both rodents and humans." (PMID 21999347, 2011). "Fasting plasma insulin level was elevated in obese MSG rats with insulin resistance." (PMID 21999347, 2011). "Interestingly, it has been observed that insulin seems to inhibit resistin secretion, while resistin induces insulin resistance, in an insulin-resistin-insulin sensitivity positive feedback loop." (PMID 21760816, 2011). "Interestingly, along with the rapid improvement in glucose-lipid metabolism and insulin resistance, and elevated plasma insulin, we observed a dramatic decrease in fasting plasma FGF-21 concentrations in these patients." (PMID 22046277, 2011). "The observed decrease in PKC ζ expression in adipose tissue may contribute to development of insulin resistance in the energy storage phenotype, again, demonstrating the important metabolic role of adipose tissue in the regulation of insulin sensitivity." (PMID 21835020, 2011). "Endogenous hyperinsulinemia must be treated by minimizing insulin resistance with diet, exercise and insulin sensitizing medications, whereas exogenous hyperinsulinemia must be avoided by selecting appropriate diet and life style while using minimal doses of insulin to achieve normoglycaemia." (PMID 21668983, 2011).
Insulin resistance (continued). "Insulin resistance is the state of tissues and organs with reduced sensitivity to insulin." (PMID 21801458, 2011). "In the current paradigm for type 2 diabetes, obesity results from energy imbalance, insulin resistance from obesity, and exhaustion of pancreatic beta cells from overproduction of insulin to compensate for insulin resistance, which ultimately progresses to diabetes." (PMID 21298090, 2011). "In contrast, endothelial dysfunction may lead to attenuated glucose uptake in insulin-sensitive tissues, hyperglycemia, and ultimately to the development of insulin resistance and type 2 diabetes." (PMID 21303562, 2011). "Thiazolidinediones act as insulin sentitizers by multiple mechanisms and a previous study in non-diabetic insulin resistant individuals indeed demonstrated lower insulin and improvement of insulin resistance after rosiglitazone treatment." (PMID 22035351, 2011). "Nevertheless, IL-18 levels have been have been consistently associated with insulin resistance measured by the homeostasis model assessment (HOMA) and studies in humans and il18−/− mice suggest a possible role for IL-18 in insulin sensitivity and energy homeostasis." (PMID 20227263, 2011). "Thus, it seems that hemin-induced HO-1 can enhance the function of β cells via increase insulin sensitivity in the insulin resistance mouse model." (PMID 22220267, 2011). "In this respect, we cannot exclude that the stimulating effect of IL-1β on β-cell function could play a part in the high plasma insulin levels that compensate for insulin resistance in obese rats." (PMID 21826222, 2011). "But as insulin resistance increases, the counter-regulatory measures within islets may become dysfunctional or overridden by high insulin levels, leading to increased α-cell turnover and ultimately more glucagon released into the circulation." (PMID 21283589, 2011). "While peripheral insulin resistance is common during obesity and aging in mice and people, progression to T2D is largely due to insulin secretory dysfunction and significant apoptosis of functional β cells, leading to an inability to compensate for insulin resistance." (PMID 22164157, 2011). "However, there was a marked insulin resistance determined by fasting insulin levels, peak insulin levels, and homeostasis model assessment (HOMA)." (PMID 21904547, 2011). "In contrast, several other studies debate the actual insulin-mimetic properties of visfatin, with such studies identifying a lack of association between visfatin and insulin resistance in humans, at either circulating or mRNA levels." (PMID 21694775, 2011). "We tried to find out the role of H2S in insulin secretion and in development of insulin resistance." (PMID 21264117, 2010). "This enhanced secretion of insulin may represent a homeostatic mechanism to compensate for an increase in peripheral insulin resistance." (PMID 20488778, 2010). "OPN KO mice fed HFD for 2 weeks were completely protected from the severe skeletal muscle, liver and adipose tissue insulin resistance that developed in wild type (WT) controls, as determined by hyperinsulinemic euglycemic clamp and acute insulin-stimulation studies." (PMID 21103061, 2010). "Direct measurement of insulin resistance is difficult and therefore in order to help clinicians identify persons who might be insulin resistant a clinically defined entity - the metabolic syndrome - was first proposed by the World Health Organization (WHO)." (PMID 21134291, 2010). "On the other hand, insulin resistant persons also have a characteristic dyslipidemia and measuring these variables might help identify insulin resistance." (PMID 21134293, 2010). "However, serum RBP4 levels correlated with endogenous insulin secretion (C-peptide) and insulin resistance (HOMA index)." (PMID 20932285, 2010).
Insulin resistance (continued). "Severity of inflammatory lesions on the face, insulin sensitivity (homeostasis modeling assessment of insulin resistance), androgens and insulin-like growth factor-1 and its binding proteins were assessed at baseline and at eight weeks, a period corresponding to the school term." (PMID 22253996, 2010). "Chronically elevated insulin concentrations may promote vascular lesion formation; in patients with insulin resistance, such as those with metabolic syndrome, there is an increased risk of cardiovascular disease." (PMID 21203503, 2010). "Why the patients with type 1 diabetes had a greater response to acute insulin, compared to controls, may be because of the presence of generalized insulin resistance." (PMID 20573241, 2010). "Of them, 36.2% of the prediabetic adults had insulin resistance and 63.8% had insulin sensitive." (PMID 21187864, 2010). "Insulin resistance induced by increased inducible NO synthase in obesity may be related to S-nitrosation of insulin signalling proteins, insulin receptor, insulin receptor substrate 1 and protein kinase B (Akt)." (PMID 21135801, 2010). "Insulin resistance is considered a key feature of these diseases and is defined as a state requiring more insulin in order to obtain the biological effects achieved with a lower insulin level in the normal state." (PMID 20181067, 2010). "T2DM is characterized by both insulin resistance (as manifested by reduced insulin-stimulated glucose uptake in skeletal muscle and adipose tissue and inappropriately high hepatic glucose output) and reduced insulin secretion by pancreatic β-cells." (PMID 20369014, 2010). "However, given that many insulin resistant patients are normotensive, further studies are needed to fully characterize the P13K/Akt-signaling and calcium efflux in hypertension and insulin resistance." (PMID 20508722, 2010). "The observation of hyperinsulinism in 92% of our patients with IGT confirm that insulin resistance is a strong predictor of the two-hour plasma glucose levels in youngsters, and the presence of high insulin levels in 100% of diabetics shows that beta-cell function was still preserved." (PMID 20920305, 2010). "For detecting insulin resistance, numerous techniques such as euglycemic clamp technique, insulin tolerance test, insulin sensitizing test, IV/oral glucose tolerance test, fasting insulin levels, fasting glucose to insulin ratio have been devised by several investigators." (PMID 21234175, 2010). "Moreover, per- and postoperative aggravated insulin resistance and hyperglycemia are apparently important factors in studies documenting the effect of postoperative tight glycemic control with insulin therapy on morbidity and mortality." (PMID 21156037, 2010). "Despite decades of progress in under-standing insulin-mediated signal transduction, the molecular mechanisms underlying insulin resistance are complex, and are not fully explored." (PMID 20952811, 2010). "Therefore, chronic sitagliptin treatment has promoted a reduction of glucose and HbA1c levels, together with a partial correction of insulin reduction and an improvement of insulin resistance (HOMA-IR), which is in agreement with other reports." (PMID 20652060, 2010). "We found that women in the lower SES stratum were more likely to have elevated insulin resistance and fasting insulin levels compared with women in the higher SES stratum, but we did not observe similar differences for men, consistent with published observations." (PMID 20394692, 2010). "In animal in vitro studies, green tea increased the basal and insulin-stimulated glucose uptake of rat adipocytes, suppressed glucose absorption in the rabbit small intestine, and ameliorated insulin resistance by increased expression of glucose transporter IV in rat adipocytes." (PMID 21118565, 2010).
Insulin resistance (continued). "Also, a growing body of evidence indicates that mice without the capacity to synthesize the a-series GM3 ganglioside display an increased insulin sensitivity, and these mutant mice are protected from high-fat-diet-induced insulin resistance." (PMID 21087515, 2010). "Also, the levels of insulin, C-peptide and homeostasis model assessment for insulin resistance (HOMA-IR) significantly decreased in all subjects." (PMID 20181067, 2010). "However, insulin resistance specifically refers to the inability of insulin to promote cellular glucose uptake, which is mediated primarily via the phosphatidylinositol-3 kinase (PI3K) signalling pathway downstream of the insulin receptor." (PMID 21054880, 2010). "Short-term ghrelin/GHS administration stimulates GH secretion, locomotor activity, and appetite, increases plasma free fatty acids, imposes mild peripheral (muscle) insulin resistance, suppresses insulin secretion, inhibits fat oxidation, and promotes adipocyte glucose metabolism." (PMID 20798846, 2010). "One mechanism by which high salt might precipitate insulin resistance is through its ability to enhance an oxidative stress-induced inflammatory response that disrupts the insulin signaling pathway." (PMID 20678234, 2010). "In addition to glucose tolerance test, we also measured fasting insulin levels in the blood as additional parameters for insulin resistance." (PMID 20633301, 2010). "In patients with T2D, insulin resistance is a product of decreased insulin-stimulated skeletal muscle glycogen synthesis, which can mostly be attributed to decreased insulin-stimulated glucose transport (Glut 4) activity and similar alterations have been observed in maternal skeletal muscle in GDM." (PMID 21052542, 2010). "Studies from our laboratory showed that VSMC from obese, insulin-resistant Zucker fa/fa rats—the classical animal model of insulin resistance due to defects in leptin receptors—show a reduced insulin ability to increase NO synthesis, and a reduced response to the NO/cGMP/PKG pathway." (PMID 20652043, 2010). "It has been proposed that suppression of insulin signaling in insulin resistance interferes with protective actions of insulin such as endothelial NO production and anti-inflammatory effects and thus leads to a chronic state of (pro)inflammation, representing a hallmark of atherosclerosis." (PMID 21049052, 2010). "It is well established that AMPK enhances insulin sensitivity and ameliorates insulin resistance." (PMID 20167101, 2010). "In addition HOMA mostly describes hepatic insulin resistance and steady-state insulin secretion due to the calculation from the fasting plasma glucose and insulin values." (PMID 20805868, 2010). "Insulin resistance, an inability of the insulin to increase glucose uptake and use, may also be implicated in hyperglycemia in AP." (PMID 27956981, 2010). "The pathophysiology of insulin resistance involves a complex network of insulin signaling pathways." (PMID 20182627, 2010). "We then aimed to elucidate whether impaired insulin secretion or rather insulin resistance may be responsible for this phenotype." (PMID 20876939, 2010). "Hence, the characterization of transcriptional modifications in endothelium is an important step for a better understanding of the mechanism of insulin action and the relationship between endothelial cell dysfunction and insulin resistance." (PMID 21203503, 2010). "As HOMA-IR primarily reflects hepatic insulin resistance and SI captures both hepatic and peripheral insulin sensitivity, dietary vitamin D may be more related to hepatic insulin sensitivity than peripheral insulin sensitivity." (PMID 20398267, 2010). "The primary aim of this randomised control trial (RCT) is to determine the efficacy and effectiveness of two different structured lifestyle interventions differing in diet composition on insulin sensitivity, in adolescents with clinical insulin resistance and/or prediabetes treated with metformin." (PMID 20868506, 2010).